RNU6-1098P (RNA, U6 small nuclear 1098, pseudogene)
Gene: Small nuclear RNA gene on chromosome 3 (149,525,631 to 149,525,726, forward strand). Ensembl gene ENSG00000252581.
Homologues: Orthologues: chimpanzee U6 (96% identical), macaque U6 (95% identical), pig U6 (74% identical), rat LOC120095711 (73% identical), guinea pig U6 (71% identical). Paralogues in human: RNU6-1145P (89% identical), RNU6-1316P (88% identical), RNU6-393P (88% identical), RNU6-411P (88% identical), RNU6-151P (86% identical), RNU6-20P (86% identical), RNU6-283P (86% identical), RNU6-35P (86% identical), RNU6-38P (86% identical), RNU6-477P (86% identical), RNU6-698P (86% identical), RNU6-961P (86% identical), and 1288 more.